RNU1-105P (RNA, U1 small nuclear 105, pseudogene)
Gene: Small nuclear RNA gene on chromosome 6 (47,823,390 to 47,823,550, forward strand). Ensembl gene ENSG00000200340.
Homologues: Orthologues: chimpanzee U1 (99% identical), macaque U1 (84% identical), rat U1 (72% identical). Paralogues in human: RNU1-1 (78% identical), RNU1-2 (78% identical), RNU1-27P (78% identical), RNU1-28P (78% identical), RNU1-3 (78% identical), RNU1-4 (78% identical), RNVU1-18 (78% identical), RNVU1-29 (78% identical), U1 (78% identical), RNU1-89P (77% identical), RNVU1-28 (77% identical), RNVU1-7 (77% identical), and 134 more.